EGFR (epidermal growth factor receptor)
Diseases named in the same sentence as EGFR in open-access papers (continued):
Sharing a sentence is not in itself a finding about the gene and the disease.
lung adenocarcinoma (continued). "Similar results were obtained in a earlier study involving the massively parallel sequencing of 22 lung adenocarcinoma specimens, which revealed that EGFR mutations can be very heterogeneous in a single tumor sample and that certain mutations were only present in <10% of total sequences." (PMID 25780439, 2015). "The frequency of common EGFR mutation in adenocarcinoma, which depends on the patients’ background, ranges from 15 to 45%, suggesting that the common EGFR mutation is a frequent and important event of lung adenocarcinomas." (PMID 26090892, 2015). "In particular, the EGFR-L858R mutation may play a role in the development of MPE in lung adenocarcinoma patients." (PMID 26338423, 2015). "EGFR mutations were found in 11.5% of Sardinian patients with lung adenocarcinoma." (PMID 25683726, 2015). "In this study, we investigated if MET gene copy number status as assessed by FISH could predict the clinical outcome for EGFR-TKI in EGFR-mutated lung adenocarcinoma patients." (PMID 25886066, 2015). "Therefore, the anti-EGFR TKIs gefitinib, erlotinib and afatinib are currently employed for the treatment of patients with advanced lung adenocarcinoma harboring EGFR activating mutations." (PMID 25904052, 2015). "In a proportional hazard analysis performed in another study, we found that the application of the VNR + DIF combination but not platinum-based chemotherapy was a significant and independent factor to prolong survival in lung adenocarcinoma patients with EGFR mutations (unpublished data)." (PMID 25573239, 2015). "According to a recent meta-analysis of 94 studies, the rate of EGFR mutation in lung adenocarcinoma in Asians (47.9%) is higher than that in Westerners (19.2%), while KRAS (11.2%) and LKB1 (4.0%) mutation rates are lower in Asians than in Westerners (26.1% and 16.2%, respectively)." (PMID 25760072, 2015). "Moreover, in AdSqLCs, a relatively high frequency of EGFR mutations (mut-EGFR) is described, thereby patients with AdSqLCs are treated as lung adenocarcinoma." (PMID 26422230, 2015). "In this study, we hypothesized that specific genetic alterations may underlie the primary resistance to EGFR-TKIs in lung adenocarcinoma harboring activating EGFR mutations." (PMID 25823662, 2015). "Our NGS-based multi-gene mutation profiling of lung adenocarcinomas carrying the activating EGFR mutation L858R has uncovered an MLH1 V384D allele that is over-represented in a subset of tumors showing primary resistance to EGFR-TKIs." (PMID 25823662, 2015). "EGFR is the second most frequently mutated oncogene in lung adenocarcinoma after KRAS." (PMID 25730908, 2015). "EGFR overexpression and activity could result in tumor growth and progression and somatic mutations within the tyrosine kinase domain of EGFR, which have been identified in a subset of lung adenocarcinoma." (PMID 26185761, 2015). "Pre-gefitinib MET FISH status may be useful for predicting PFS and OS after Gefitinib treatment in lung adenocarcinoma with EGFR mutation and for selecting the patients who would benefit from EGFR-TKI and MET inhibitor therapy." (PMID 25886066, 2015). "Our study demonstrates that the 1st-line chemotherapy followed by EGFR-TKIs in patients with EGFR mutation advanced lung adenocarcinoma had a better OS than that of the 1st-line TKIs followed by 2nd-line chemotherapy in these patients (median: 662 versus 390 days, p < 0.0001)." (PMID 26609535, 2015). "NSCLCs harboring-activated EGFR mutations are addicted to EGFR signaling, and treatment with small-molecule EGFR-tyrosine kinase inhibitors (TKIs) such as gefitinib and erlotinib demonstrated dramatic responses to lung adenocarcinomas with EGFR mutations." (PMID 25573239, 2015). "However, almost all lung adenocarcinoma patients with EGFR mutations who respond to EGFR-TKIs ultimately develop resistance to these agents." (PMID 25573239, 2015).
lung adenocarcinoma (continued). "We explored the efficacy and survival of Gefitinib for young patients with unknown epidermal growth factor receptor (EGFR) gene mutation of advanced lung adenocarcinoma." (PMID 24854557, 2014). "In this study, we analyzed exome sequencing data from 16 EGFR/KRAS/ALK-negative tumors and paired normal samples and an applicable expansion cohort of 54 EGFR/KRAS-negative lung adenocarcinomas to identify novel somatic mutations in lung adenocarcinomas of never-smokers." (PMID 24576404, 2014). "However, gefitinib is the first targeted agent to be approved for the treatment of EGFR mutation-positive lung adenocarcinoma, which has showed evident clinical efficacy, particularly among non-smokers, East Asian females and patients with adenocarcinoma." (PMID 25120716, 2014). "Currently, tumor tissues obtained by surgery or biopsy (including thoracoscopic pleural metastatic tissue biopsy) are commonly used for EGFR mutation test, but unfortunately, it is difficult to obtain adequate amount of tumor tissues from patients with advanced lung adenocarcinoma." (PMID 24587142, 2014). "Recent molecular studies of NSCLC find that mutations of the EGFR gene are present in 10-20% of lung adenocarcinomas (ADC) and are associated with successful treatment with EGFR inhibitors, whereas KRAS mutations are present in 20-30% of ADC and associated with non-response to EGFR inhibitors." (PMID 25346886, 2014). "Based on this data, we hypothesize that TTF-1 expression in lung adenocarcinoma patients is correlated with EGFR mutations." (PMID 24743427, 2014). "These mutations can co-exist with other known driver mutations in lung adenocarcinoma, including EGFR and KRAS and in the setting of acquired EGFR TKI resistance, suggesting that this may not be a driver mutation in itself." (PMID 25505733, 2014). "The relationship between TTF-1 and EGFR mutation in lung adenocarcinomas." (PMID 24743427, 2014). "The purpose of this study is to analyze the EGFR gene mutation rates in MPEs and matching MPTTs obtained by thoracoscopic pleural metastatic tissues biopsy from patients with advanced lung adenocarcinoma and determine if MPEs are good substitutes for MPTTs in EGFR gene mutation test." (PMID 24587142, 2014). "However, only patients with lung adenocarcinoma with EGFR mutations or anaplastic lymphoma kinase (ALK) rearrangements have an FDA-approved therapy available." (PMID 24587185, 2014). "According to the Catalogue of Somatic Mutations in Cancer (COSMIC) (v66) database, 9.5% (524 of 5544 reported cases) of the EGFR mutations in lung adenocarcinoma may be undetected by modern MtS methods, a finding which was similar to that of our study." (PMID 25215536, 2014). "In our clinically enriched series (Caucasian women with lung adenocarcinoma) we aimed at investigating the possible predictive significance of EGFR and K-Ras mutations with respect to both first-line platinum-based CT and salvage treatment with the anti-EGFR TKI erlotinib." (PMID 25300933, 2014). "The median PFS and OS of the young patients with Unknown EGFR gene mutation in advanced lung adenocarcinoma were similar with general population." (PMID 24854557, 2014). "Furthermore, AXL and its ligand Gas6 were similarly observed to be upregulated along with vimentin upregulation and E-cadherin loss in the COR cell clones resistant to the EGFR T790M-targeting drug, CO-1686 in EGFR-mutated lung adenocarcinoma." (PMID 25337673, 2014). "Of the 301 lung adenocarcinomas samples 224 were positive for EGFR mutations (74%)." (PMID 25594059, 2014). "The clinical data of 55 young patients with unknown EGFR gene mutation in advanced lung adenocarcinoma referred to the Cancer Hospital & Institute, Chinese Academy of Medical Sciences from Jan 2006 through Dec 2010 were analyzed retrospectively." (PMID 24854557, 2014).
lung adenocarcinoma (continued). "The high concordance of EGFR mutation statuses between MPEs and MPTTs in lung adenocarcinoma patients with pleural metastasis as determined by ARMS analysis suggests that MPEs, particularly MPE supernatants, may be substitutes for MPTTs in EGFR mutation test." (PMID 24587142, 2014). "In this context, it is worth noting and described in more detail below, that clinical studies with the TKIs Gefitinib and Erlotinib showed significantly improved survival in patients suffering from lung adenocarcinoma harboring mutations in the kinase domain of EGFR." (PMID 24879454, 2014). "In lung adenocarcinomas loss of PTEN expression in EGFR-mutant cells correlates with increased drug resistance, but the rarity of the deletion observed entails the hypothesis that loss of expression is not due to a genomic alteration of PTEN." (PMID 25160065, 2014). "Furthermore, three genes were among the top 20 most frequently mutated genes in lung adenocarcinoma: EGFR (34%), ATM (5%) and KDR (5%)." (PMID 24646369, 2014). "EGFR mutations were detected in 43 (31.2%) of the 138 lung adenocarcinoma patients." (PMID 23425899, 2013). "Another study observed that somatic mutations of EGFR were discordant between primary tumors and corresponding pleural metastases in a significant portion of lung adenocarcinomas, although the mutation frequency was higher in primary lesions compared with pleural metastases." (PMID 24137392, 2013). "Material obtained via endobronchial ultrasound (EBUS)-transbronchial needle aspiration (TBNA) may also be useful for detecting EGFR mutations in patients with lung adenocarcinoma, since positive results were previously demonstrated in ~1/10 Spanish patients." (PMID 23817662, 2013). "We examined lung adenocarcinoma tissues from 138 patients, including 68 Uighur lung adenocarcinoma patients and 70 Han lung adenocarcinoma patients, for EGFR mutations in exons 18, 19, 20, and 21 by using the amplification refractory mutation system (ARMS) PCR method." (PMID 23425899, 2013). "However, none of the studies suggesting serum CYFRA 21–1 as a prognostic factor in patients with untreated advanced lung adenocarcinoma has included the EGFR mutation status as a variable." (PMID 23879483, 2013). "In lung adenocarcinoma, the mutational spectrum is dominated by EGFR and KRAS mutations." (PMID 24205279, 2013). "In addition, it was shown that OS in the KRAS mutation group was significantly poorer than those in the EGFR mutation or in both wild groups with completely resected lung adenocarcinoma." (PMID 23724098, 2013). "Based on previous findings, we proposed that -216G/T in the EGFR promoter may be associated with an increased risk of the pleural metastasis of lung adenocarcinoma." (PMID 24137392, 2013). "We also identified an increased baseline level of autophagy that may act as a protective mechanism underlying ER in EGFR mutated lung adenocarcinoma." (PMID 23119048, 2012). "The purpose of this study is to clarify the correlations between the expression of membrane-bound estrogen receptor-α (mERα) and epidermal growth factor receptor (EGFR) mutation and clinicopathological factors, especially in relation to the prognosis, in patients with lung adenocarcinoma." (PMID 22784503, 2012). "In this work, we tested the hypothesis that TWIST1 and mutated EGFR could similarly cooperate in promoting EMT in lung adenocarcinomas." (PMID 22272264, 2012). "In addition, we restricted the tumor size of the adenocarcinomas to tumors measuring less than 3 cm in diameter, because EGFR mutation is considered an early event in the pathogenesis of lung adenocarcinoma." (PMID 22784503, 2012). "Since SMPC of lung adenocarcinoma may be associated with a high incidence of EGFR mutations, EGFR-TKI may be effective against SMPC(+) tumors." (PMID 22225786, 2012).
lung adenocarcinoma (continued). "Given the observation that EGFR mutation lung adenocarcinoma is more commonly found in women compared to men, several studies have evaluated the association between ER expression and epidermal growth factor receptor (EGFR) mutation." (PMID 24213497, 2012). "Clinical detection of oncogenic point mutations conferring enzymatic gain-of-function has been a fruitful strategy for triaging patients to molecularly targeted therapy in several cancer types, including lung adenocarcinoma (EGFR mutations) and melanoma (BRAF V600E mutations)." (PMID 22194861, 2011). "Mutations affecting the extracellular domain of EGFR, often accompanied by gene amplification, are frequent in glioblastomas, while mutations in the tyrosine kinase domain of EGFR, also frequently associated with increased EGFR gene copy numbers, are clinically relevant in lung adenocarcinoma." (PMID 21403829, 2011). "EGFR has also been found to be significantly mutated in lung adenocarcinoma." (PMID 21211025, 2011). "In the course of our EGFR mutational screening in lung adenocarcinoma patients from the area of Asturias, Northern Spain, we found a tumour sample with a double somatic mutation in EGFR gene; one of the changes was demonstrated to be present as a germ-line mutation." (PMID 21575252, 2011). "In this study, 63.9% (85/133) of patients with lung adenocarcinomas had EGFR mutations." (PMID 20637128, 2010). "As with lung adenocarcinomas, mutations in the EGFR tyrosine kinase domain may be associated with clinical efficacy of EGFR inhibitors in the treatment of SGCs." (PMID 19174819, 2009). "Activating and tyrosine kinase inhibitor (TKI) sensitizing mutations in the EGFR gene are thus very rare in ovarian cancer in contrast to adenocarcinoma of the lung in which the mutation rate varies between 5 – 45% depending on the phenotypic selection criteria and ethnic background of patients." (PMID 18182111, 2008). "For example, in the target population of lung adenocarcinoma patients harboring epidermal growth factor receptor (EGFR) tyrosine kinase domain mutations, treatment with EGFR tyrosine kinase inhibitors can achieve long-lasting responses in a high proportion of patients." (PMID 16401350, 2006). "However, the prognostic impact of RICTOR mutations in epidermal growth factor receptor (EGFR)-mutant lung adenocarcinoma remains unclear." (PMID 42080921, 2026). "Thus, we hypothesize that all mutations of these 2 critical glycines could impact loop flexibility and thus activation, as previously demonstrated for G-loop mutations in EGFR in lung adenocarcinoma." (PMID 40831936, 2025). "In lung adenocarcinoma studies in the Chinese population, carriers of the rs1897990‐T allele had a significantly increased risk (OR = 1.32, 95% CI: 1.08–1.60), possibly related to aberrant activation of EGFR signalling driven by EGF overexpression in the tumor microenvironment." (PMID 40696566, 2025). "Although in this study, the EGFR mutation rate was almost unrelated to the differentiation grade (P=0.0546), the incidence rate of EGFR mutation in patients with moderately differentiated lung adenocarcinoma was higher than patients with well differentiated adenocarcinoma (P =0.0162)." (PMID 40182027, 2025). "Furthermore, research has also focused on identifying the epidermal growth factor receptor (EGFR) gene mutation status in lung adenocarcinoma, which is crucial for determining the use of EGFR-tyrosine kinase inhibitors (EGFR-TKIs) and thus beneficial for personalized patient care." (PMID 40475956, 2025).
lung adenocarcinoma (continued). "In addition, this study provides the first clinical evidence demonstrating that savolitinib effectively reverses acquired resistance to EGFR-TKIs driven by novel METex14 skipping mutation in patients with advanced lung adenocarcinoma harboring EGFR mutations, thereby yielding long-term PFS benefits." (PMID 40129940, 2025). "The efficiency and optimal combination strategies of immune checkpoint inhibitors (ICI) in lung adenocarcinoma (LUAD) patients with epidermal growth factor receptor (EGFR) other mutations apart from 19del/L858R (classical), which account for up to 20% EGFR mutations, remains unclear." (PMID 41162774, 2025). "TB and malignancy may coexist in about 2% of cases, often causing discordance between radiological, histopathological, and microbiological findings, and the coexistence of TB with EGFR-mutated lung adenocarcinoma has been documented in a few case reports and case series." (PMID 41141063, 2025). "If a ground-glass nodule is determined to harbor an EGFR mutation, EGFR-targeted therapy may be considered for the management of the remaining lesions in patients with multiple GGNs, thus supporting the precision treatment of lung adenocarcinoma." (PMID 41357203, 2025). "Therefore, the primary objectives of this study were to characterize the immunohistochemical expression of DARPP-32 isoforms in canine lung adenocarcinoma, and to evaluate associations with clinical variables, EGFR and VEGFR2 immunohistochemical expression, and outcome." (PMID 40969344, 2025). "The EGFR mutation in lung adenocarcinoma patients may also influence the pattern of metastasis." (PMID 39193383, 2024). "Also, hypopharyngeal cancer may potentially spread to lung adenocarcinoma with EGFR mutation, and lung adenocarcinoma with EGFR mutation may potentially metastasize to hypopharyngeal cancer." (PMID 38783639, 2024). "Therefore, detecting MUC21D may serve as a prognostic indicator for predicting the recurrence of EGFR-mutated lung adenocarcinomas." (PMID 38933439, 2024). "Epidermal growth factor receptor (EGFR) is the most common mutant gene in lung adenocarcinoma, especially EGFR-positive mutations play an important role in the occurrence of brain metastasis in lung adenocarcinoma, but there is still uncertainty and controversy in related studies." (PMID 38605303, 2024). "Notably, Osimertinib, a third-generation EGFR-TKI, effective against both EGFR-sensitive mutations and T790M resistance mutations, has made substantial progress in the treatment of advanced lung adenocarcinoma, especially as a first-line therapy and in the management of brain metastases." (PMID 39772073, 2024). "Moreover, the development of EGFR-mutated lung adenocarcinomas may also be associated with MUC21 protein, which exhibits specific glycosylation states." (PMID 38933439, 2024). "Likewise, the association of nuclear shape irregularities and specific molecular alterations that contributed to increased malignancy have been established in some other cancers, such as papillary thyroid carcinoma with RET fusion and EGFR mutated lung adenocarcinomas." (PMID 38972973, 2024). "Thus, we can claim that patients with EGFR‐mutated lung adenocarcinoma may have the potential to develop hypopharyngeal cancer, according to the preceding statistic." (PMID 38783639, 2024). "However, the intrinsic impact of the PD-L1 expression status on postoperative recurrence in EGFR-mutated lung adenocarcinoma remains unknown." (PMID 39281386, 2024). "Furthermore, in an analysis of 860 patients with lung adenocarcinoma who were prospectively tested for actionable mutations, one patient (100%) with an EGFR L833V mutation in conjunction with an EGFR L858R substitution mutation who received EGFR TKI therapy and chemotherapy had clinical benefit." (PMID 39497876, 2024). "Therefore, the expression of PD-L1 may indicate high malignant potential through the strength of its downstream signaling in EGFR-mutated lung adenocarcinoma." (PMID 39281386, 2024).